EZH2 (enhancer of zeste 2 polycomb repressive complex 2 subunit)
Diseases named in the same sentence as EZH2 in open-access papers (continued):
Sharing a sentence is not in itself a finding about the gene and the disease.
cancer (continued). "In stem cells and cancer cells, EZH2 generates H3K27me3 marks at nucleosomes near the promoters of developmental genes, represses transcription, and thus prevents differentiation to support the proliferative state in stem cells or neoplasia in cancer." (PMID 30253781, 2018). "In 2010, an additional mechanism of EZH2 dysregulation in cancer was reported." (PMID 29685962, 2018). "These indicate a potential role of EZH2 in DC function, and whether EZH2 regulates DC-based cancer immunotherapies is worth further investigation." (PMID 29556394, 2018). "We have demonstrated that silencing EZH2 or treatment of EZH2 inhibitors in cancer cells inhibit in vitro angiogenesis of endothelial cells, which provides direct evidences supporting a role of EZH2 in cancer cells contributing to angiogenesis." (PMID 30287808, 2018). "Accumulating evidences have shown that the expression and activity of EZH2 in cancer cells can be regulated at genetic, transcriptional, post-transcriptional and post-translational levels, which may explain these diverse functions of EZH2." (PMID 29556394, 2018). "Because EZH2 deregulation, notably overexpression, is frequently found in a variety of cancers, EZH2 has become an interesting therapeutic target for the development of anti-cancer drugs." (PMID 28717873, 2018). "The lysine methylase EZH2 methylates histone H2B at lysine 120, which is a site of ubiquitylation, inhibits ubiquitylation and suppresses the transcription of genes involved in cancer." (PMID 30344952, 2018). "Finally, various miRNA targeted EZH2 mRNA and inhibit migration and invasion in various cancer cell lines." (PMID 34991274, 2018). "Thus, EZH2 is a potential target for cancer therapy, and EZH2 inhibitors have been under intense pre-clinical and clinical investigation." (PMID 29556394, 2018). "Here, we will systematically discuss the functions of dysregulated EZH2 in cancers as below." (PMID 29556394, 2018). "Numerous studies have suggested that EZH2 might be a meaningful prognostic factor for multiple survival assessments in a variety of cancers." (PMID 30542123, 2018). "Compared with patients with low expression of EZH2, the hazard ratios of overall death and cancer-related death for those with high EZH2 expression were 2.15 (range 1.01–4.56) (p = 0.047) and 3.51 (range 1.08–11.38) (p = 0.037), respectively, in the univariate models." (PMID 30542123, 2018). "The critical roles of EZH2 in drug resistance of cancer cells were also identified." (PMID 29556394, 2018). "EZH2 has gained interest as a marker of aggressive subgroups in several cancers." (PMID 30469511, 2018). "Through H3K27me3, EZH2 represses genes involved in both differentiation and cancer." (PMID 29853899, 2018). "Furthermore, we found that PTEN/Akt signaling contributed to the effects of Ezh2 on cancer stem cells (CSC) and EMT phenotype in GC cells, and blocking PTEN signaling significantly rescued the effects of Ezh2." (PMID 29335012, 2018). "The result showed that enforced expression of EZH2 substantially reversed the inhibitory effects of combined therapy on the key malignant features such as cellular migratory ability and the colony-forming potential of cancer cells." (PMID 30555330, 2018). "As pEZH2 T367 is also expressed in the cytoplasm of human carcinomas of other organs compared to normal tissues, our findings may shed light into a common mechanism of EZH2 in human cancer." (PMID 30022044, 2018). "Suppression of EZH2 promotes cancer progression in some cancer types." (PMID 29556394, 2018). "It has been reported that inhibition of the methyltransferase EZH2 may represent a novel treatment strategy for ARID1A mutant cancers." (PMID 29760405, 2018). "EZH2 plays varied roles in cancer development relying on the type of cancers." (PMID 29089464, 2018). "EZH2 is overexpressed in many cancer types and is proved to act as an oncogene." (PMID 30266084, 2018). "The role of EZH2 in cancer have been extensively reviewed elsewhere." (PMID 30761216, 2018).
cancer (continued). "Diverse SWI/SNF mutated cancers exhibit dependence on both catalytic and non-catalytic functions of EZH2, a core subunit of PRC272–74." (PMID 30202034, 2018). "Enhancer of zeste homolog 2 (EZH2), a methyltransferase that di- and tri-methylates lysine-27 of histone H3, largely functions as a transcriptional repressor, and plays a critical role in various kinds of cancers." (PMID 29416002, 2018). "EZH2, an inhibitor of gene transcription, was related to biological malignancy in various cancers." (PMID 29089464, 2018). "However, a systematic study of EZH2 expression and DNA promoter methylation in most human cancers is still needed." (PMID 30469511, 2018). "Whether Ezh2 is involved in the oncogenesis and development of other human malignancies via the PTEN/Akt signaling is still worth exploring, and the results would help us to better understand the role of Ezh2 in cancer." (PMID 29335012, 2018). "We next directly assessed the contribution of EZH2 expression in cancer cells to angiogenesis." (PMID 30287808, 2018). "Additionally, GSK126, a common EZH2 inhibitor, is an effective treatment both in monolayer systems as well as xenografts in various types of cancers, decreasing proliferation, angiogenesis and increasing apoptosis." (PMID 29710783, 2018). "The role of EZH2 in cancer progression was also considered and unraveled." (PMID 29556394, 2018). "Members of PRC2—in particular, Ezh2—are often found dysregulated in human cancers." (PMID 30080881, 2018). "We also know that cancer cells present a very variable genotype and that EZH2 and KDM6B could drive a specific cell phenotype depending on the cellular context." (PMID 34991274, 2018). "Since patients often develop resistance to olaparib, our results suggest that PARP1 inhibitors might be combined with EZH2 inhibitors to improve cancer therapy." (PMID 29535829, 2018). "Several cancer-related studies have revealed that MALAT1 is capable of binding to enhancer of zeste homolog 2 (EZH2), the main catalytic subunit of the histone methyltransferase polycomb repressive complex 2 (PRC2), and promotes oncogenesis by reprograming the chromatin state." (PMID 29695738, 2018). "LAT1 not only supports mTORC1 activity, it also reinforces MYC and EZH2 signaling in cancer cells." (PMID 30103560, 2018). "Increasing evidence indicates that enhancer of zeste homolog 2 (EZH2), the catalytic subunit of Polycomb repressor complex 2, is highly expressed in cancer stem cells of numerous malignant tumors and has a critical function in cancer stem cell expansion and maintenance." (PMID 28415635, 2017). "EZH2 is overexpressed in many cancers and correlates with poor prognosis." (PMID 29061982, 2017). "EZH2 is frequently overexpressed in various cancers and is critical for cancer cell proliferation." (PMID 29228709, 2017). "Overexpression EZH2 is important for cancer progression in several cancer types." (PMID 28561778, 2017). "GSK2816126 is a highly selective and potent inhibitor of both wild type and mutant EZH2, decreases H3K27 tri-methylation, releases transcriptional repression of PRC2 target genes, and induces anti-proliferative activity in several wild type and mutant EZH2 cancer cell lines." (PMID 29262669, 2017). "Curcumin has been shown to block cancer metastasis via induction of let-7 and suppression of EZH2, NF-κB, and LIN28 expression, and we recently demonstrated that curcumin inhibits A549 cell migration and invasion via negative regulation of NF-κB/MMPs signaling." (PMID 28587210, 2017). "The function of EZH2 in malignant tumors may due to its transcriptional repression of differentiation-related and antimetastatic genes." (PMID 28415635, 2017). "Finally, our study showed that EZH2 is extraordinarily upregulated in cancer cells, although the mechanism for this is unclear and further research is required." (PMID 28416772, 2017).
cancer (continued). "The differential expression and enrichment of EZH2 in cancer, compared to normal cells may suggest that the PRC2 complex plays an essential role in the selection and recognition of methylated nucleotide substrates." (PMID 28416772, 2017). "This situation leads to ambiguity in defining CSCs and may lead to variable results regarding EZH2 expression in CSCs in different types of cancer." (PMID 28415635, 2017). "EZH2 constitutes the main component of PRC2 as a transcriptional repressor and dysregulation of EZH2 is implicated in progression of many types of human cancers including ESCC." (PMID 29100288, 2017). "The trimethylation of H3K27 by EZH2 pre-marks genes for DNA methylation in cancer." (PMID 28261562, 2017). "EZH2 enhances tumorigenesis and is commonly upregulated in various types of cancers including PCa." (PMID 29141691, 2017). "In conclusion, regardless of whether it functions as a classical oncogene or a CSC-specific regulator, novel anti-cancer therapeutic strategies will emerge from further research on the molecular mechanisms of EZH2 action in CSC regulation." (PMID 28415635, 2017). "We focused here on how MUC1-C activates EZH2 based largely on its dysregulation in cancer." (PMID 28785086, 2017). "EZH2 silences several miRNAs in various human cancers, suggesting that it may indirectly activate important oncogenes through modulating miRNAs." (PMID 28088786, 2017). "And EZH2 can be regarded as a suppressor of cancer progression." (PMID 28423699, 2017). "Furthermore, several studies have reported that EZH2 inhibition increases the sensitivity of different cancer cells to radiation and chemotherapy." (PMID 28642877, 2017). "Finally, we will review the development, translation and early clinical findings of therapeutics targeting EZH2 in cancer." (PMID 28410242, 2017). "EZH2 has been found to play pivotal roles in the development of various cancers." (PMID 28679390, 2017). "Previous evidence showed that EZH2 promoted cancer cells to proliferate, metastasis and invade." (PMID 27880940, 2017). "In addition to enzymatic inhibition, some natural compounds have also been proven to be effective in repressing the expression level and function of EZH2 in several malignant tumor types." (PMID 28415635, 2017). "Therefore, as a new biomarker, EZH2 can be considered to be a novel target for the treatment of malignant tumors." (PMID 28415635, 2017). "Thus, EZH2-targeting drugs have become attractive weapons in cancer therapy and research effort on developing enzymatic inhibitors is fueled." (PMID 28978137, 2017). "It has been reported that EZH2 is essential for the initiation and development of various cancers." (PMID 28332284, 2017). "Inhibitors of EZH2 are in development, and their role in cancer treatment is being studied." (PMID 28359267, 2017). "Whole genome analysis has indicated that the downstream targets of EZH2 are cancer specific." (PMID 28410242, 2017). "However, few studies of systematic mining EZH2 specific miRNA signature in human cancers have been reported." (PMID 29221202, 2017). "Therefore, EZH2 is a potential target for cancer therapy and a variety of inhibitors have been developed and their effects on cancers are going to be widely examined." (PMID 28561778, 2017). "This dual role in cancer and development is not unique to SETBP1; a growing number of genes in which germline mutations cause developmental disorders, such as HRAS, ASXL1, EZH2 and FGFR2, are also known to harbor overlapping somatic mutations which drive the development of cancer." (PMID 28346496, 2017). "EZH2 plays a role in cancer progression through several mechanisms, including gain-of-function and loss-of-function mutations, overexpression of EZH2, mutations in the H3K27 demethylase gene, and through antagonistic mutations in the SWI/SNF chromatin remodeling complex." (PMID 29093822, 2017). "Such knowledge might help to understand how to use EZH2 inhibitors in combination for cancer treatment." (PMID 27472460, 2016).
cancer (continued). "Therefore, our data suggest that LDM reduces EZH2 while inducing p21 protein expression upon senescence development in the cancer cells." (PMID 27882937, 2016). "In addition to cancer cells, EZH2 also has a decisive role in the differentiation and function of T effector and T regulatory cells." (PMID 27793053, 2016). "Agents with a dual capability to effectively inhibit DNA methyltransferase and EZH2 enzyme activity might be potentially useful in the prevention and/or treatment of cancer." (PMID 27658199, 2016). "Overexpression of EZH2 results in hyper activation found in a variety of cancer." (PMID 27713574, 2016). "EZH2 is a histone methyltransferase that is frequently overexpressed in various human cancers." (PMID 26973857, 2016). "We predicted genome-wide potential targets and the role of EZH2 in regulating as a transcriptional suppressor or activator which could pave the way for mechanism studies and the targeted therapy of EZH2 in cancer." (PMID 27835578, 2016). "This highlights the importance of EZH2 and DNMTs as key epigenetic regulators and therapeutic targets that function through a common mechanistic pathway and silence gene expression related to the initiation and maintenance of cancer." (PMID 27658199, 2016). "Taken together, EZH2 plays an essential and multi-faceted role in human cancers." (PMID 26683709, 2016). "EZH2 has been to play an important role in a variety of different cancers." (PMID 27385092, 2016). "Small molecule inhibitors of EZH2 have recently been discovered, and a number of these compounds are currently being clinically developed as a promising therapeutic for the treatment of cancer." (PMID 27875550, 2016). "EZH2 has been shown to promotes tumorigenesis in many types of cancers." (PMID 27494834, 2016). "Taken together these studies strongly suggest that regulation of EZH2 at the post-translational level might be of particular importance with regards to its activity and implication in cancer development and growth." (PMID 27793053, 2016). "The exactness of the mechanisms by which EZH2 impacts cancer needs further investigation." (PMID 27119045, 2016). "For example, EZH2 accelerates cancer cell migration by repressing TIMP3 expression in NSCLC cells." (PMID 27058897, 2016). "The data suggest that targeting EZH2, which is often overexpressed in cancer, might be a useful approach to sensitize anticancer therapy or overcome drug resistance." (PMID 27472460, 2016). "Additionally, EZH2 has been identified as a transcriptional activator of several genes in various cancers, but the mechanisms are less well characterized as compared to the role of EZH2 within the PCR2 complex." (PMID 27764181, 2016). "Knockdown EZH2 has been shown to induce apoptosis in different cancers." (PMID 27223261, 2016). "EZH2 plays a specific role in apoptosis and mediates the degree of it in many cancers." (PMID 27706111, 2016). "In sunitinib-treated RCC tissues, loss of antitumor miR- 101 may lead to upregulation of UHRF1 and EZH2, and consequently, post-transcriptional modification of multiple genes would promote cancer-related phenotypes in cells." (PMID 27487138, 2016). "Together, these reports indicate that LINC00152 might be a key regulator in the development of cancer because of its ability to increase EZH2-dependent gene silencing." (PMID 26799422, 2016). "In the era of cancer immunotherapy, therapeutic targeting EZH2 will pose new challenges." (PMID 27793053, 2016). "Finally, we discuss EZH2 function with respect to amount of trimethylated H3K27, in a specific cellular milieu, through presenting the most recent data related to EZH2-H3K27m3 relationship in cancer." (PMID 27239242, 2016). "Accumulating evidence indicates that EZH2 is involved in fundamental cellular processes, such as cell proliferation and differentiation, cell cycle regulation and fate decision, carcinogenesis, cancer stem cell maintenance, and drug resistance." (PMID 27223261, 2016).
cancer (continued). "With more insights into the mechanisms of EZH2 in more cancer types, targeted therapy of EZH2 may apply to more cancer types and combination of other chemotherapies could be considered to overcome the drug resistance in clinical." (PMID 27835578, 2016). "EZH2 inhibitors have gained great interest for their use as anti-cancer therapeutics." (PMID 27634879, 2016). "However, most research has focused on EZH2 mutant cancers and recently adverse effects of EZH2 inactivation have come to light." (PMID 27634879, 2016). "EZH2 inhibitor DZNep has been shown to induce apoptosis in different cancer cells." (PMID 27223261, 2016). "Overexpression and dysregulated of EZH2 are frequently observed in multiple types of cancer." (PMID 27468692, 2016). "Given the currently evolving development of EZH2 inhibitors for human malignancies, the introduction of these inhibitors as modulators of immune-mediated diseases and activation of the immune system in patients with cancers is a promising opportunity." (PMID 27199994, 2016). "EZH2 is up-regulated in various cancer types, implicating its role in tumorigenesis." (PMID 27385092, 2016). "EZH2 deregulation has been described in many cancer types including hematological malignancies." (PMID 26497210, 2016). "Apart from its role as a chromatin modulator or direct activator of oncogenic pathways, EZH2 can alter signaling pathways in cancer cells by posttranslational mechanisms that alter the properties of key signaling molecules, further supporting the complexity of EZH2 involvement in cancer biology." (PMID 27793053, 2016). "Our in silico studies, we further demonstrated the ability of flavones to bind to the catalytic pocket of EZH2 and, in a cell culture study with nucleotides obtained from cancer cells, flavones demonstrated the ability to inhibit EZH2 enzyme activity and protein expression." (PMID 27658199, 2016). "The biological effects of the EZH2/HOX axis may depend on its specific function in different cancers or in different disease stages within a single cancer type." (PMID 26812882, 2016). "Studies revealing the mechanisms of EZH2 in tumorigenesis may provide insights into the drug interaction or resistance in cancer treatment." (PMID 27835578, 2016). "Previous studies showed that EZH2 is a critical predictor of cancer prognosis." (PMID 27172794, 2016). "Other lncRNAs (e.g., EBIC, H19, PVT1, and MALAT1) also interact with EZH2 in cancer cells, and may promote malignancy in GC by altering EZH2 activity." (PMID 26799422, 2016). "Therefore, we conclude that cell cycle arrest is a pivotal contributor to the eradication of CS-like cells to cure cancer via the regulation of EZH2 expression." (PMID 27172794, 2016). "In addition, EZH2 promotes epithelial-mesenchymal transition (EMT), a process that is associated with cancer progression and metastasis, by interacting with transcription factor SNAIL1 and suppressing expression of epithelial marker E-cadherin (CDH1)." (PMID 26683709, 2016). "EZH2 plays critical roles in embryonic stem cells, adult stem cells and cancer." (PMID 26349457, 2016). "EZH2 catalyses the trimethylation of histone 3 lysine 27 (H3K27me3) and mediates the silencing of target genes involved in fundamental cellular processes, such as cell fate decision, cell cycle regulation, cell differentiation, senescence and cancer." (PMID 27191993, 2016). "Carcinomas showed higher EZH2 expression level than hyperplastic lesions." (PMID 27502594, 2016). "Given that EZH2 expression is increased in advanced carcinomas and that EZH2 expression is essential for CRC cell growth, we hypothesized that EZH2 is differentially expressed between CS-like cells and non-CS-like cells." (PMID 27172794, 2016). "EZH2 is expressed in CMTs, and its levels correlate with carcinoma malignancy." (PMID 27502594, 2016). "EZH2 is one of the first histone lysine methyltransferases found to be related to human cancers." (PMID 26258118, 2015).